ASH1L (ASH1 like histone lysine methyltransferase)
Diseases named in the same sentence as ASH1L in open-access papers (continued):
Sharing a sentence is not in itself a finding about the gene and the disease.
bone tumors (1 paper, 2025). "Compared to the control group, the ASH1L-depleted bone tumors showed a remarkable reduction in lipid-associated TAM (MC5), proliferating TAMs (MC7), and angiogenic TAMs (M4), along with a dramatic increase in monocyte/TAM intermediate cells (MC3)." (PMID 40394007, 2025). "To deconvolute the impact of ASH1L on invading cancer cells and metastatic bone niches, we performed single-cell RNA sequencing (scRNA-seq) in control (n = 3) and ASH1L-depleted (n = 4) syngeneic bone tumors." (PMID 40394007, 2025). "Reversely, overexpression of ASH1L in cancer cells suppressed monocytes but promoted pro-tumoral TAMs in bone tumors." (PMID 40394007, 2025). "To characterize their subtypes and activation states in metastatic bone niches and determine ASH1L’s impact, we performed clustering and differential gene expression analyses of monocytes (C3) and TAMs (C4) in control and ASH1L-depleted bone tumors." (PMID 40394007, 2025). "Cells from control and ASH1L-depleted bone tumors were distributed in all ten clusters, and each cluster contained cells from seven samples." (PMID 40394007, 2025). "Of note, inhibiting ASH1L only impaired bone tumor outgrowth in the presence of macrophages, while depletion of macrophages abolished these effects, suggesting TAMs are required for ASH1L’s pro-metastatic role." (PMID 40394007, 2025). "Compared to that of control tumors, TAMs in ASH1L-depleted bone tumors showed significant elevation in inflammation pathways, including IFN signaling, TNF signaling, IL-1/2 signaling, cGAS-STING, and antigen processing and presentation pathway." (PMID 40394007, 2025). "Immunofluorescence staining not only verified the depletion of total TAMs (both F4/80+CD206+ and F4/80+CD206-) in the bone tumors after CSF1R blockade but confirmed the suppressing effects of ASH1L inhibition on pro-tumoral TAMs (F4/80+CD206+) in the bone niche." (PMID 40394007, 2025). "Besides, genes involved in senescence and pyroptosis pathways were significantly upregulated in TAMs upon ASH1L depletion in bone tumors, whereas cell cycle and mitosis-related genes were downregulated." (PMID 40394007, 2025). "Importantly, our preclinical and human-relevance studies demonstrate the therapeutic potential of targeting ASH1L in metastatic bone tumors, providing insights into targeted therapies in patients with lethal malignancies." (PMID 40394007, 2025). "Furthermore, we performed multiplex IHC staining in those bone tumors and found that pro-tumoral TAMs (F4/80+CD206+) were significantly reduced in ASH1L-expressing tumors upon HIF-1α inhibitor treatment." (PMID 40394007, 2025).
co-infection (1 paper, 2021). "Most of DREADD-expressing pyramid neurons had Ash1L knockdown (96 ± 1.5% co-infection, n = 3 mice)." (PMID 34782621, 2021).
cognitive decline (1 paper, 2021). "This timing of the cognitive decline is consistent with our study design wherein we identified methylation changes in ASH1L and TNIK after 1 week of high-altitude exposure." (PMID 34262470, 2021).
colon cancer (1 paper, 2024). "In colon cancer cells treated with the deacetylase inhibitor sulforaphane (SFN), acetylation of CCAR2 in the C-terminus established an acetyl ‘switch’ site, whereas acetylation in the N-terminus provided recognition motifs for the bromodomains of BAZ1A and ASH1-like protein (ASH1L)." (PMID 39112459, 2024).
congenital heart disease (1 paper, 2023). A heart disease that is present at birth. "Variants in the genes that encode the H3K36 methyltransferases, NSD1, NSD2, and, ASH1L, have been linked to congenital heart disease." (PMID 37504562, 2023). "Variants in ASH1L have been associated with congenital heart disease in patients." (PMID 37504562, 2023).
dementia (1 paper, 2024). Loss of intellectual abilities interfering with an individual's social and occupational functions. "Using a large European sample, a genome-wide association study demonstrated that ASH1L was the closest gene to a dementia with Lewy bodies-related locus on chromosome 1." (PMID 39765675, 2024). "However, ASH1L has a potential association with dementia with Lewy bodies, which has a 31% genetic overlap with AD and PD." (PMID 39765675, 2024).
dilated cardiomyopathy (1 paper, 2023). Cardiomyopathy which is characterized by dilation and contractile dysfunction of the left and right ventricles. "ASH1L is expressed in both fetal and adult human heart tissue, and was differentially expressed in cardiac tissue from patients with dilated cardiomyopathy (with heart failure)." (PMID 37504562, 2023).
epidermal disease (1 paper, 2017). A skin disease that involves the epidermis. "The relation between Ash1l mutation and human epidermal diseases remains unclear." (PMID 28374742, 2017).
epilepsy syndrome (1 paper, 2024). A syndrome that has a characteristic cluster of clinical features and/or lectroencephalographic (EEG) findings that reflect underlying epileptic activity. "Overall, familial cases in this cohort were more likely to exhibit variants in genes associated with established epilepsy syndromes, such as ASH1L, SLC12A5, and DEPDC5." (PMID 39767570, 2024).
gout (1 paper, 2022). A condition characterized by painful swelling of the joints, which is caused by deposition of urate crystals. "Three LD blocks existed in chromosome 1 for the variants relating to gout, which were composed of genes DNAJC16, AGMAT (first block), PDZK1, CD160, NUDT17 (second block), TRIM46, MUC1, MTX1, and ASH1L (third block)." (PMID 36221101, 2022).
kidney cancer (1 paper, 2019). Primary or metastatic malignant neoplasm involving the kidney. "In contrast, mRNA levels of WHSC1L1, ASH1L, and NSD1 were more than onefold lower in kidney cancer cell lines." (PMID 30755832, 2019).
metastatic cancers (1 paper, 2025). A carcinoma which has spread from the original site of growth to another anatomic site. "We uncovered that ASH1L is genetically amplified and overexpressed in diverse metastatic cancer types." (PMID 40394007, 2025). "Specifically, 46% and 35% of the downregulated DEGs (FDR ≤0.05; FC ≥1.5) showed decreased H3K4me3 and H3K36me3 signals, respectively (p values of overlap <1e-300, by Fisher’s exact test), suggesting that these genes (n = 1180) are the most likely direct targets of ASH1L in metastatic cancer cells." (PMID 40394007, 2025).
metastatic tumors (1 paper, 2025). "We found that ASH1L was genetically amplified and overexpressed in metastatic tumors and was associated with disease progression and worse prognosis." (PMID 40394007, 2025). "High ASH1L mRNA levels are correlated with genetic amplification status and are strongly associated with metastatic diseases." (PMID 40394007, 2025). "Compared to the ASH1L-low group, lipid-associated TAMs are much more abundant in metastatic tumors expressing high levels of ASH1L, along with enriched HIF-1α transcriptome in cancer cells." (PMID 40394007, 2025). "These preclinical studies demonstrated the therapeutic potential of targeting ASH1L in metastatic diseases." (PMID 40394007, 2025). "Given that the ASH1L gene is amplified and overexpressed in metastatic diseases, we further determined the impact of ASH1L overexpression on PCa cell migration, invasion, and metastasis." (PMID 40394007, 2025). "Based on ASH1L expression in epithelial cells, we classified 13 metastatic tumors into two groups, ASH1L-high (n = 5) and ASH1L-low (n = 8)." (PMID 40394007, 2025). "We found that ASH1L was highly expressed in invasive cancer cells and metastatic tumors in male PbPPS mice." (PMID 40394007, 2025). "The results indicated that metastatic tumors containing ASH1L gene gain or amplification had a higher abundance of TAMs." (PMID 40394007, 2025).
neuroblastoma (1 paper, 2017). Neuroblastoma (NB) is the most common solid, extracranial childhood tumor. "Interestingly, however, ASH1L has been found to be over-expressed in neuroblastoma cell line transfected with normal or mutated alpha-synuclein." (PMID 28899360, 2017).
Obesity (1 paper, 2022). Accumulation of substantial excess body fat. "ASH1L and GAK were previously reported to be associated with obesity traits such as BMI and waist-hip ratio in GWAS of UK Biobank39." (PMID 36329257, 2022).
osteoporosis (1 paper, 2022). A condition of reduced bone mass, with decreased cortical thickness and a decrease in the number and size of the trabeculae of cancellous bone (but normal chemical composition), resulting in increased fracture incidence. "Levels of ASH1L were reduced in mice osteoporosis models as well as human osteoporotic samples, indicating a positive correlation of Ash1l expression with bone mass." (PMID 35481717, 2022).
ovarian carcinoma (1 paper, 2020). A malignant neoplasm originating from the surface ovarian epithelium. "By analyzing the TCGA database and performing HR repair screening, we demonstrated that three BRD-containing proteins, BRD9, ASH1L, and ZMYND8, positively regulate HR, and the mutations of these three BRD-containing proteins are associated with HR-deficient mutational signatures in ovarian cancer." (PMID 32457312, 2020).
prostate tumors (1 paper, 2025). "Besides, we found that genetic amplification of ASH1L was associated with worse overall survival in men with metastatic PCa, and human prostate tumors with high ASH1L mRNA levels exhibited an enriched cancer metastasis profile." (PMID 40394007, 2025). "Phenocopying ASH1L depletion, the blockade of CSF1R significantly suppressed the outgrowth of prostate tumors in the bone." (PMID 40394007, 2025).
rheumatoid arthritis (1 paper, 2017). A chronic, systemic autoimmune disorder characterized by inflammation in the synovial membranes and articular surfaces. "Furthermore, ASH1L, SMAD3 and FOXP3 are all downregulated in CD4+ T cells from PBMCs of patients with rheumatoid arthritis, indicating the potential significance of ASH1L/SMAD3/FOXP3 pathway in human autoimmune pathogenesis." (PMID 28598443, 2017). "Lastly, ASH1L, FOXP3 and SMAD3 are downregulated in peripheral CD4+ T cells from patients with rheumatoid arthritis." (PMID 28598443, 2017).
Seizure (1 paper, 2024). A seizure is an intermittent abnormality of nervous system physiology characterized by a transient occurrence of signs and/or symptoms due to abnormal excessive or synchronous neuronal activity in the brain. "Seizures have been observed in children carrying ASH1L mutations." (PMID 39766886, 2024).
cancer (19 papers, 2017 to 2025). A tumor composed of atypical neoplastic, often pleomorphic cells that invade other tissues. "With the exception of the singular H3K36me3-depositing SETD2, which appears to unambiguously function as a tumor suppressor, the remaining H3K36 methyltransferases (NSD1, NSD2, NSD3, and ASH1L) are all implicated in or associated with various cancers." (PMID 39403928, 2024). "ASH1L was found to be upregulated in thyroid, breast, and liver cancers and was linked to enhanced cancer cell growth and aggressiveness of the tumor." (PMID 36674511, 2023). "Furthermore, we identified an unrecognized regulatory axis of ASH1L-IGF-2 in invading cancer cells, which induces lipid-associated and angiogenic TAMs and maintains their pro-tumoral and anti-inflammatory phenotypes by enhancing OXPHOS." (PMID 40394007, 2025). "In addition, the overexpression of ASH1L was found in thyroid, breast, and liver cancers, and is associated with enhanced cancer cell growth and aggressive disease." (PMID 33990599, 2021). "Combining it with single-cell transcriptomics, we determined the role of ASH1L in modulating the communication between disseminated cancer cells and host immune cells in the bone niche." (PMID 40394007, 2025). "Consistent with single-cell transcriptome analysis, inhibition of ASH1L in cancer cells dramatically decreased TAMs with pro-tumoral phenotype (F4/80+CD206+) and led to an increase in tumor-infiltrating monocytes (Ly6c+) in the bone niche." (PMID 40394007, 2025). "The histone H3K36-specific methyltransferase ASH1L plays a critical role in development and is frequently dysregulated in human diseases, particularly cancer." (PMID 40044670, 2025). "More importantly, we identified ASH1L as a key epigenetic regulator mediating the crosstalk between invading cancer cells and TAMs in the metastatic bone niche." (PMID 40394007, 2025). "X-ray imaging and histopathology analysis revealed that ASH1L depletion in invading cancer cells protected cortical bone from absorption and reduced new woven bone production." (PMID 40394007, 2025). "These transcriptional and epigenetic studies demonstrate that ASH1L governs the transcriptional activation of pro-metastatic genes in invading cancer cells via reprogramming histone methylations at H3K4 and H3K36." (PMID 40394007, 2025). "In cellular experiments, we showed that AS-99, a small-molecule inhibitor against ASH1L, suppressed cancer cell migration and invasion." (PMID 40394007, 2025). "It indicates that ASH1L in invading cancer cells contributes to the proliferation, survival, and anti-inflammatory phenotype of TAMs." (PMID 40394007, 2025). "In this study, we reported that the ASH1L/HIF-1α complex in invading cancer cells promotes IGF-2 expression, which triggers AKT-GSK3b-mTOR signaling and activates OXPHOS pathways in monocytes in the bone niche." (PMID 40394007, 2025). "To verify if methyltransferase activity is required for ASH1L’s role in promoting cancer invasiveness, we constructed a catalytically inactive mutant of ASH1L-F3, F2260A16,32, and then introduced it into LNCaP cells." (PMID 40394007, 2025). "Collectively, these studies in human samples, GEM models, and cancer cell lines demonstrate that histone methyltransferase ASH1L is genetically amplified and overexpressed in metastatic PCa, among other malignancies." (PMID 40394007, 2025). "Immunohistochemistry (IHC) staining of ASH1L in human PCa tumors revealed that ASH1L protein levels were positively correlated with cancer progression and aggressiveness." (PMID 40394007, 2025). "Our studies establish ASH1L as an essential HMT that drives cancer invasiveness and bone metastasis." (PMID 40394007, 2025). "Bioluminescence imaging showed that depletion of ASH1L suppressed the metastasis of cancer cells to the tibia, femur, or mandible." (PMID 40394007, 2025).
cancer (continued). "Altogether, these loss-of-function and gain-of-function studies establish the crucial role of ASH1L in driving cancer invasiveness and bone metastasis via its methyltransferase activity." (PMID 40394007, 2025). "Then, we performed high-throughput transcriptomic and epigenetic profiling to dissect the molecular basis of ASH1L’s role in transforming invading cancer cells." (PMID 40394007, 2025). "In a meta-analysis of human cancers, we found that amplification and gain of the ASH1L gene occur in >40% of metastatic PCa, much more frequently than in localized tumors." (PMID 40394007, 2025). "Mechanistically, ASH1L co-opts with HIF-1α to induce a pro-metastatic transcriptome in cancer cells via catalyzing histone methylations at H3K4 and H3K36." (PMID 40394007, 2025). "The IVIS and ex vivo GFP-fluorescence imaging showed that genetic knockout of ASH1L in cancer cells significantly suppressed tumor outgrowth in the bone." (PMID 40394007, 2025). "Although studies have confirmed ASH1L’s oncogenic role in cancer, research demonstrating its involvement in AD, PD, or HD is lacking." (PMID 39765675, 2024). "In breast cancer, higher ASH1L levels were observed in the basal subtype, the one that exhibits cancer stem cell-like traits." (PMID 36674511, 2023). "To date, molecular studies confirming ASH1L involvement in the regulation of cancer de-differentiation status in solid tumors are missing." (PMID 36674511, 2023). "Kyoto Encyclopedia of Genes and Genomes (KEGG) pathway enrichment analysis demonstrated that upon ASH1L knockdown, targeted genes were significantly enriched in cancer-related pathways, such as apoptosis, focal adhesion, cellular senescence, and cell cycle." (PMID 36033518, 2022). "In TP MO, ASH1L is seen to regulate highest number of processes that include apoptosis, carbon metabolism in cancer and NFκB signaling pathway." (PMID 34976314, 2022). "The histone methyltransferase ASH1L plays a role in various diseases, including cancer, and has been validated as a therapeutic target; however, no inhibitors of ASH1L have been reported." (PMID 33990599, 2021). "This compound can serve as a valuable chemical probe to further explore the biological functions of ASH1L and to address a potential therapeutic benefit of blocking ASH1L in different diseases, including cancer." (PMID 33990599, 2021). "As a TF, if ASH1L displays abnormal regulation, it will lead to many diseases, such as cancer and neurological diseases." (PMID 28719625, 2017). "Amplification and genetic alterations of ASH1L (absent, small or homeotic discs 1-like) have been linked to a wide array of human diseases, including cancer and autoimmune, developmental and neurodegenerative disorders." (PMID 40044670, 2025). "Furthermore, we assessed the relevance of ASH1L amplification or overexpression with cancer progression, clinical outcomes, and immunophenotype in men with metastatic PCa." (PMID 40394007, 2025). "Gene set enrichment analysis (GSEA) also revealed a significant downregulation of the hypoxia pathway and HIF-1α target genes upon ASH1L depletion, particularly those involved in cancer cell invasion (Snail, TGFB, and MET), extracellular matrix remodeling (MMPs and PLAU), and angiogenesis (VEGFs)." (PMID 40394007, 2025). "According to TCGA, the ASH1L gene is frequently altered in human cancers." (PMID 40044670, 2025). "By epigenetically reprogramming invading cancer cells, ASH1L not only induces tumor-infiltrating monocyte differentiation into lipid-associated and angiogenic TAMs, but also suppresses antigen presentation, interferon signaling, and immunostimulatory molecule expression in inflammatory TAMs." (PMID 40394007, 2025). "As in other tumor types, ASH1L might be associated with OCCC biology, and since epigenetic regulators are considered important targets for cancer treatment, our observation opens a new research opportunity to define the role of ASH1L in OCCC." (PMID 37400764, 2023).